MYC (MYC proto-oncogene, bHLH transcription factor)
Diseases named in the same sentence as MYC in open-access papers (continued):
Sharing a sentence is not in itself a finding about the gene and the disease.
cancer (continued). "Both MYC and SP1 expression correlate with TERT transcription in various cancer cell lines." (PMID 33802026, 2021). "We observed that MYC-amplified but not SMARCA4-mutant cancer cells were sensitive to these treatments." (PMID 34262032, 2021). "In bladder cancer, METTL3 was upregulated in patient samples, and it benefits cancer progression by mediating several m6A modification targets (CDCP1, ITGA6, AFF4, IKBKB, RELA, and MYC), in which YTH family served as the binding protein of the target transcripts." (PMID 35117988, 2021). "Although the downregulation of MYC transcription has been widely proposed as a key mechanism for BET inhibitor anti-tumor activity, additional mechanisms for BET inhibitor efficacy against cancer have also been reported." (PMID 34298819, 2021). "It was reported that miR-106b may stimulate cancer cell growth through targeting DAB2, FUT6, MYC, and multiple mechanisms." (PMID 34519258, 2021). "Alternatively, in already transformed cancer cells and particularly in SCC cancer cells, USP28 acts as an oncoprotein facilitating cancer homeostasis and proliferation via stabilization of oncogenic substrates, such as c-MYC, c-JUN, NOTCH1, ∆Np63, and CCNE." (PMID 34685632, 2021). "Among the genes downregulated after MLL1 and MLL2 downregulation in our RNA-seq data, we detected three additional transcription factors with known roles in cancer: MYC, PAX2, and BAHCC1 (data not shown)." (PMID 34381018, 2021). "To date, acquired resistance to BETi treatment has never been studied in a MYC-independent cancer type, such as LAC, limiting the ability to combat other forms of BETi resistance in the clinical setting." (PMID 33712563, 2021). "Furthermore, RPLP1 and RPL28 expression in BKZ-8 was affected by KJ-Pyr-9 application, suggesting an involvement of MYC signaling in ribosomal biosynthesis of AC-derived LCSC-like cells, as already shown for several cancer types." (PMID 33925297, 2021). "The CTLA4, TOB1, MYC, Notch, Hedgehog, and EMT pathways play a critical role in cancer progression." (PMID 34095215, 2021). "The linkage of proline metabolism is not limited to cancer but is also evident in viral proliferation as seen in the hijacking of proline biosynthetic enzymes (PYCR1) by Kaposi’s sarcoma herpes virus K1 and MYC-dependent adenoviral proliferation." (PMID 34825974, 2021). "Given most cancers have deregulated MYC expression, and as a consequence, BCL-2 pro-survival proteins are often also deregulated to counter the pro-apoptotic effect of high MYC expression, there is a strong rationale for co-targeting of MYC and BCL-2 proteins in many cancers." (PMID 33799592, 2021). "Chromatin modifiers such as histone methyltransferases have been defined as promising targets for many cancer types, including hematologic malignancies, although not necessarily through MYC inhibition only." (PMID 35582389, 2021). "We propose that, once cancer cells spontaneously acquire cisplatin resistance, we can use a PARP inhibitor (instead of a still-controversial MYC inhibitor) to inhibit oncogenic MYC activity so that we can recover endogenous BIN1 expression and accompanying cisplatin sensitivity." (PMID 34948122, 2021). "This means that not all cancer cells with abundant MYC will be absolutely dependent on MYC for proliferation and survival." (PMID 33760847, 2021).
cancer (continued). "Here, WDR12, MYC, WDR3, are critical in the regulation of cell cycle progression in cancer cells." (PMID 34131166, 2021). "In several cancer cell lines, the CTCF binding site upstream of the MYC promoter accounts for long-distance interactions with cancer-specific downstream super-enhancers, which result in elevated MYC expression." (PMID 34209337, 2021). "Despite the intensive interests, MYC and HIF1α have not been successfully targeted for clinical cancer treatment." (PMID 33572152, 2021). "“MYC”, “BMI1”, “MEL18”, and “KRAS” collections played oncogenic roles in cancer course." (PMID 34094897, 2021). "Notably, previous studies revealed that IGF2BP1, acted as a m6A reader, played an oncogenic role in cancer cells, through stabilizing methylated mRNAs of oncogenic proteins, including FSCN1, TK1, MARCKSL1, and MYC." (PMID 33853613, 2021). "Calcitriol stimulation highlighted an inhibitory effect on CCAT2’s regulatory activity by decreasing the affinity between the transcription factor TCF7L2 and the MYC promoter, hindering its expression and therefore supporting a possible place for calcitriol as an inhibitor of CCAT2 in cancer." (PMID 34830370, 2021). "The upregulation of HIF under hypoxia microenvironment has been shown to induce the expression of known pluripotent stemness factors, such as KLF4, MYC, OCT4, SOX2, and NANOG, to reprogram towards a cancer stem cell (CSC) phenotype and to influence the expansion of CSC populations." (PMID 34798868, 2021). "MYC, CDKN2A, PTEN, HARS, APC2, and APC are often referred to as miRNAs in cancer." (PMID 33959508, 2021). "Further supporting the possibility of targeting MYC-dependent cancer cells through WNK1 inhibition, we find evidence in an orthogonal drug repurposing screen that cells with high expression of MYC or dependence on MYC have increased sensitivity to PP121 treatment." (PMID 33328249, 2021). "In this regard, we recently showed that GPS = 3 + 3/PGG1 bioptic cores from upgrading patients may already harbor genomic lesions typical of more aggressive cancers, such as PTEN deletion or MYC amplification." (PMID 34069838, 2021). "In summary, our data demonstrated that MYC and HIF1α protein were degraded through proteasome dependent pathways, by the β-TrCP- and VHL-dependent mechanisms, respectively, in echinomycin-treated cancer cells." (PMID 33572152, 2021). "Upon T cell activation, let-7 levels are reduced, MYC is derepressed and the metabolic switch from OXPHOS to glycolysis occurs in order to obtain a proper cytotoxic T cell response towards virus-infected cells or antigen-loaded cancer cells." (PMID 33401522, 2021). "In cancer, TERT has been shown to bind TCF binding elements (TBEs) to drive c-MYC expression." (PMID 33599797, 2021). "The proto-oncogene MYC is tightly regulated in non-cancerous cells due to its oncogenic potential, but is dysregulated in greater than 50% of human cancers." (PMID 34073112, 2021). "Since BCL-2 family members and MYC act cooperatively in cancers, inhibiting MCL-1 could be a potential approach for MYC-involved cancers." (PMID 34372899, 2021). "The fact that many cancer cells cannot survive without MYC – a phenomenon termed “MYC addiction” – provides a compelling case for the development of MYC-specific targeted therapies." (PMID 34676047, 2021). "Some roles described for the physiological functions of the cell are exploited by cancer cells to their advantage to allow the self-renewal of the cancer stem cells, to increase translation of oncogenes such as EGFR, MYC, TAZ, MAPKAPK2 and to use shelter systems to allow cell survival." (PMID 34530916, 2021). "Because c-MYC affects the expression of a myriad of genes involved in these processes, the expression of c-MYC must be tightly regulated to prevent the development of cancers." (PMID 33513764, 2021).
cancer (continued). "Importantly, we observed that c-MYC expression was positively correlated with eIF4A1 expression in PDAC and across various cancer types (n = 44, r = 0.5041, P = 0.0005, Spearman correlation)." (PMID 34906136, 2021). "Indeed, c-MYC has been demonstrated to be a key regulator of ASCT2 and GLS in cancer, thus promoting Gln uptake and glutaminolysis." (PMID 34445444, 2021). "Both mTOR and c-MYC are well-known master regulators of cellular metabolism and have been shown to regulate the TCA cycle and mitochondrial function, thus driving metabolic rewiring in cancer 68-70." (PMID 33754045, 2021). "Therefore, the TAD of MYC, MB2, and MYC:TRRAP are required for MYC-driven transactivation and cancer promotion." (PMID 34676047, 2021). "In several cancer models, chronic hypoxia and HIF-2α appear critical, either by favoring CSCs self-renewal via WNT and NOTCH signaling pathways or by modulating cyclin expressions through c-MYC activation for example." (PMID 34539584, 2021). "Previously, oncogenic MYC activation was shown to confer stress on splicing machinery via upregulation of PRMT5, which makes the spliceosome an attractive target in MYC-driven cancers." (PMID 34002025, 2021). "The model indicated that sustained cancer regression is difficult to achieve in the absence of the immune system ven if MYC is inactivated arly(e.g., at diagnosis)." (PMID 33446671, 2021). "Since inhibitors of BET proteins, including OTX and structurally similar inhibitors to JQ1, are currently in clinical trials for several cancers, it is more likely that combination of TEM with BET inhibitors can be translated in clinic for NB and other MYC/MYCN-driven cancers therapies." (PMID 34565342, 2021). "The differentially expressed proteins were identified in the signaling pathways of granzyme B, sirtuins, eIF2, actin cytoskeleton, eNOS, acute phase response and calcium and were connected to the upstream regulators MYC, PI3K SMARCA4 and cancer-related chemical drugs." (PMID 33656060, 2021). "In addition to MYC, SAGA components also regulate cancer development through post-translational modifications of other non-histone substrates such as chromatin modifiers." (PMID 34112237, 2021). "Additionally, by forming protein complexes with other proteins such as MYC, WDR5 induces the expression of key oncogenes, leading to tumor initiation, cell cycle progression, DNA replication, invasion, and cancer metastasis." (PMID 34201935, 2021). "In addition to degrading total and chromatin-bound WDR5, MS67 also decreased chromatin-bound fractions of MLL complex components, such as MLL, RBBP5, and Menin, and c-MYC, another WDR5 partner in cancer." (PMID 34586829, 2021). "MYC and PGC-1α are key regulatory proteins for glycolysis and oxidative phosphorylation, respectively, suggesting that miR-494 plays an important role in energy metabolism in cancer cells." (PMID 35008652, 2021). "The HHT mode of action in this cancer has not been precisely demonstrated although HHT decreased the cellular levels of MYC, MCL-1, SURVIVIN and also interfered with JAK1 and STAT3 phosphorylation, to decrease the levels of IL6, a growth factor for NSCLC." (PMID 32151059, 2020). "Correlation of MYC+TWIST1 expression with CCL2 and IL13 in TCGA pan-cancer cohort (n = 9502)." (PMID 31933479, 2020). "In addition, the protein CDR1, an APCCDH1 substrate, binds c-MYC to activate its transactivation; elevated accumulation of CDR1 in cancer cells as a result of APC inhibition or defect promotes c-MYC oncogenic function." (PMID 32805721, 2020). "In several cancers, it has been demonstrated that YAP stimulates cell proliferation largely by controlling the expression of a broad number of cell cycle regulators or the expression of oncogenes, for example MYC and AP-1 family members." (PMID 33419295, 2020).
cancer (continued). "Therefore, the use of prolinamides to target the promoter region of oncogenes, such as c-MYC and BCL-2, is a promising route towards developing effective cancer therapies." (PMID 33047051, 2020). "It was reported before that vitamin D inhibits MYC gene in cancer cells, although the mechanism was not clear." (PMID 32230936, 2020). "As aerobic glycolysis and angiogenesis are common downstream effectors of MYC and HIF, which cooperate to drive the expression of many genes involved in both processes in cancer cells, targeting Warburg effect and pro-angiogenic factors have been of great interest." (PMID 33251216, 2020). "This provides an opening to target MYC expression specifically in cancer cells without affecting MYC expression in normal cells of the patient." (PMID 32158925, 2020). "In view of lacking correlation of IGF2BP1 and MYC mRNAs across cancers, this provided further evidence that IGF2BP1-dependent regulation of MYC mRNA levels is rather cell-type specific." (PMID 32761127, 2020). "Previous studies reported that RNA m6A methylation could affect various biological processes and signaling pathways, such as self-renewal and tumorigenesis of cancer stem cells, RNA metabolism, the FTO/m6A/MYC/CEBPA signaling, and the IL-7/STAT5/SOCS pathways." (PMID 32419773, 2020). "At another dimension which might be of importance for treatment resistance in MYCN-driven cancer, involves OCT4 phosphorylation at S111 via MAPKAP2 that can promote MYC expression." (PMID 33585252, 2020). "Therefore, MYC and TWIST1 generally appear to cooperate in human cancer to elicit a cytokinome that enables metastasis through crosstalk between cancer and immune microenvironment." (PMID 31933479, 2020). "For example, the sgRNA targeting the MYC promoter that led to down-regulated MYC expression 6.2-fold in HEK293T cells showed very modest or no repressive activity in cancer cell lines with high levels of MYC expression." (PMID 33253175, 2020). "Considering that c-MYC, together with HIF1, regulates metabolic remodeling in cancer cells under hypoxic conditions, c-MYC and HIF1 may cooperate to induce metabolic shift during iPSC reprogramming as well." (PMID 32426078, 2020). "It was shown that BRD4 is highly enriched in super-enhancers that drive the expression of factors that are critical for the pathogenesis of cancer such as c-MYC, suggesting that targeting BET family proteins could be a promising approach for cancer treatment." (PMID 32286255, 2020). "Besides the MYC gene, the 8q24.21 region harbors the PVT1 lncRNA locus, expression of which is consequently elevated in various types of cancer tissues and cell lines as a result of amplifications and translocations." (PMID 33329688, 2020). "We report here that MAX operates as an unexpected integral regulator of the circadian transcriptional network in an MYC-independent manner in both cancer and non-cancerous cell lines." (PMID 32225100, 2020). "An interesting finding is MMP9, MYC, MAPK1, MTOR are all in Proteoglycans in cancer." (PMID 32958005, 2020). "Conversely, MYCN has been shown to induce MDM2 expression in neuroblastoma cells, yet it is unclear if MYC shares this ability, if MYC family proteins upregulate MDM2 in other malignancies, and if this regulation occurs during tumorigenesis as well as in cancer cell lines." (PMID 33425720, 2020). "Consequently, we characterized the known oncogenes MYC and EGFR and the novel candidate genes ASAP1, IRF2BP2, and CCT5 as cancer drivers in promoting proliferation of TNBC cells." (PMID 32235890, 2020). "Increased levels of MYC and RAD21 can serve as indicators of dysregulated RS in cancer." (PMID 32859084, 2020). "These trials included patients of many cancer types and were not selective to MYC-amplified patients." (PMID 33322239, 2020).
cancer (continued). "The MYC- and MYCN-transformed cone precursors’ sensitivity to MDM2 knockdown suggests that MDM2 upregulation is an important part of MYC- as well as MYCN-mediated cancer initiation." (PMID 33425720, 2020). "Together, targeting these downstream signaling pathways controlled by MYC-HIF crosstalk or directly co-targeting MYC and HIFs could emerge as effective therapeutics in advanced human cancers such as advanced ccRCCs." (PMID 33251216, 2020). "Hypoxia signalling can induce HIF-dependent expression of known pluripotent factors, such as KLF4, MYC, OCT4, SOX2, and NANOG, which have an important role in the dedifferentiation process under hypoxic conditions, inducing cancer stemness and repressing cancer cell differentiation." (PMID 33339101, 2020). "Moreover, other studies revealed the importance of the co-amplification of MYC and EGFR and FGFR2, in predicting poor survival of patients undergoing cancer therapy." (PMID 32150871, 2020). "MYC has been shown to induce ESC-like characters in normal and cancer cells." (PMID 32850350, 2020). "Moreover, combined MYC and TWIST1 expression strongly correlated with the expression of M2 macrophage related genes in the pan-cancer TCGA data." (PMID 31933479, 2020). "This has been linked to a MYC-driven glycolytic programme, consistent with what is observed in induced pluripotent stem cells, leading to the notion that, rather than distinct metabolism being a ‘by-product’ of cancer stemness, metabolism may be the ‘driver’ controlling stemness characteristics." (PMID 33092283, 2020). "PIN1 regulates a large number of these cancer-related targets from extracellular receptors such as NOTCH1 or HER2, to intracellular effector proteins like RAF1 or FAK, and ultimately to transcription factors such as c-MYC, β-catenin, or NF-κB." (PMID 32300594, 2020). "In the present study, amplification in MYC and AKT1 show a strong consistency with transcript levels and glycolysis-high tumors harbor increased MYC and AKT1 expression, suggesting that AKT1 and MYC activation contribute the glycolytic activation in some cancer type." (PMID 32635458, 2020). "This study suggests a novel miR-33b/MYC/EZH2 axis that modulates the growth and the progression of breast cells and could be clinically useful to design new drugs against HER2+ subtype cancer." (PMID 33014831, 2020). "Conditioned media derived from MYC/Twist1- but not MYC-HCC cells was sufficient to promote the migration of macrophages towards cancer cells." (PMID 31933479, 2020). "Finally, we show that MYC and UBR5 are co-amplified in more than 40% of cancer cells and that MYC copy number amplification correlates with enhanced transcriptional output of UBR5." (PMID 33208877, 2020). "Thus, MYC and TWIST1 predict poor survival, CCL2/IL13 expression and M2-like TAM infiltration in human cancers." (PMID 31933479, 2020). "In addition to temporally regulating MYC activity, PIN1 regulates the subnuclear localization of MYC under normal mitogen stimulation conditions, during wound healing, and in cancer cell lines." (PMID 32300594, 2020). "This revealed that patients that had higher levels of MYC and TWIST1 proteins in their tumors also had increased levels of CCL2 and IL13, more activated macrophages and were less likely to recover from their cancer." (PMID 31933479, 2020). "Another link between MYC and UPR in cancer is the rewired metabolism." (PMID 32310340, 2020). "c-MYC was also barely detected in non-cancerous cells, but moderately stained in the cytoplasm of cancer cells." (PMID 33089188, 2020). "MYC and TWIST1 predict poor prognosis, TAM infiltration and pro-TAM cytokines in 33 human cancers." (PMID 31933479, 2020).